CXXC1 (CXXC finger protein 1)
Description:
Transcriptional activator that exhibits a unique DNA binding specificity for CpG unmethylated motifs with a preference for CpGG.
Synonyms: CFP1; CGBP; PCCX1; PHF18; HsT2645; hCGBP; SPP1; ZCGPC1; 2410002I16Rik; 5830420C16Rik
Tractability: PROTAC: UniProt records ubiquitination sites on it; ubiquitination databases record sites on it; its protein half-life has been measured.
Target class: Transcription factor
Gene: Protein-coding gene on chromosome 18 (50,282,331 to 50,287,857, reverse strand). Ensembl gene ENSG00000154832.
Subcellular location: Nucleus speckle; Nucleus
Subcellular location (Human Protein Atlas): Nucleoplasm
Pathways (Reactome):
Cellular responses to stimuli: XBP1(S) activates chaperone genes
Gene expression (Transcription): Formation of WDR5-containing histone-modifying complexes
Gene Ontology:
Molecular function: protein binding; unmethylated CpG binding; cis-regulatory region sequence-specific DNA binding; DNA binding; histone H3K4me3 reader activity; zinc ion binding
Biological process: positive regulation of DNA-templated transcription; regulation of DNA-templated transcription; chromatin organization
Cellular component: histone methyltransferase complex; nuclear speck; nucleoplasm; nucleus; Set1C/COMPASS complex; nuclear lumen; nuclear matrix
Genetic constraint (gnomAD): Loss-of-function variants: 21 observed, 81.74 expected, observed/expected ratio (o/e) 0.26, 90% interval 0.18 to 0.37. The upper end of that interval is the gene's LOEUF score, 0.37, which puts it in group 1 of 6, group 1 being the genes least tolerant of losing a copy. Missense variants: 686 observed, 940.54 expected, observed/expected ratio (o/e) 0.73, 90% interval 0.68 to 0.78. Synonymous variants: 371 observed, 348.8 expected, observed/expected ratio (o/e) 1.06, 90% interval 0.98 to 1.16.
Homologues: Orthologues: macaque CXXC1 (99% identical), chimpanzee CXXC1 (99% identical), dog CXXC1 (99% identical), pig CXXC1 (98% identical), rabbit CXXC1 (98% identical), mouse Cxxc1 (97% identical), rat Cxxc1 (97% identical), guinea pig CXXC1 (84% identical), tropical clawed frog cxxc1 (69% identical), zebrafish cxxc1a (61% identical). Paralogues in human: TAF3 (15% identical).
Diseases named in the same sentence as CXXC1 in open-access papers:
CXXC1 is named in the same sentence as 18 diseases in open-access papers, as found by Europe PMC text mining. Sharing a sentence is not in itself a finding about the gene and the disease. The quoted sentences say what the papers report.
female infertility (2 papers, 2020 to 2022). Diminished or absent ability of a female to achieve conception. "While the knockout of Cxxc1 in male germ cells using transgenic Stra8-Cre did not affect spermatogenesis and male fertility, the deletion of Cxxc1 in a Stra8-Cre knockin mouse strain resulted in male and female infertility." (PMID 33163498, 2020).
psoriasis (2 papers, 2025). An autoimmune condition characterized by red, well-delineated plaques with silvery scales that are usually on the extensor surfaces and scalp. "CXXC1 is crucial for thymocyte development, balancing Th1/Th2 and Th17/Treg dynamics relevant to psoriasis." (PMID 40650108, 2025).
autoimmune disorder (1 paper, 2025). "Treg cell-specific deletion of Cxxc1 triggers systemic autoimmunity, accompanied by multiorgan inflammation, ultimately resulting in early-onset fatal inflammatory disease in mice." (PMID 40183773, 2025). "The Treg-specific deletion of Cxxc1 leads to a rapid and fatal autoimmune disorder, characterized by systemic inflammation and tissue damage, underscoring the essential role of CXXC1 in maintaining immune self-tolerance within Treg cells." (PMID 40183773, 2025). "Given its critical role in Treg cell homeostasis, CXXC1 presents itself as a promising therapeutic target for autoimmune diseases." (PMID 40183773, 2025). "Notably, het-KO female mice did not exhibit overt signs of autoimmunity, as random X-chromosome inactivation led to the coexistence of both Cxxc1-cKO and Cxxc1-WT Treg cells." (PMID 40183773, 2025). "Thus, while YFP− WT Treg cells effectively prevent autoimmunity in het-KO mice, the absence of Cxxc1 in YFP+ Treg cells disrupts key Treg cell marker expression and impairs their suppressive function under steady-state conditions." (PMID 40183773, 2025).
bladder urothelial carcinoma (1 paper, 2021). "Patients with a higher expression level of CXXC1 had a worse prognosis for liver hepatocellular carcinoma (LIHC) but a better prognosis for bladder urothelial carcinoma (BLCA) and uterine corpus endometrial carcinoma (UCEC)." (PMID 34933446, 2021).
colitis (1 paper, 2025). Inflammation of the colon. "Finally, we examined the role of CXXC1 in Treg cell-mediated suppression using T cell transfer-induced colitis, in which naive T cells were transferred to Rag1−/− recipients either alone or together with WT or Foxp3YFP-CreCxxc1fl/fl Treg cells." (PMID 40183773, 2025). "CXXC1 is essential for Treg cells to suppress T cell-mediated experimental autoimmune encephalomyelitis (EAE) and colitis." (PMID 40183773, 2025).
experimental autoimmune encephalomyelitis (1 paper, 2025). An autoimmune demyelinating disease of the central nervous system that is produced experimentally in animals by the injection of homogenized brain or spinal cord in Freund's adjuvant. "To further assess the suppressive capacity of Cxxc1-deficient Treg cells in vivo, we employed the experimental autoimmune encephalomyelitis (EAE) model." (PMID 40183773, 2025).
glioblastoma (1 paper, 2024). The most malignant astrocytic tumor (WHO grade IV). "Neurotensin controls, via activation of the interleukin-8/ERK/CXXC1/STAT3 pathway, the stem-like traits of glioblastoma stem cells." (PMID 39063232, 2024).
glioma (1 paper, 2023). A benign or malignant brain and spinal cord tumor that arises from glial cells (astrocytes, oligodendrocytes, ependymal cells). "Investigation of its subunits WDR82, ASH2L DPY30 CXXC1, RBBP5, and WDR5 showed that WDR82 and WDR5 were significantly associated with WHO-grade malignancy in pediatric gliomas." (PMID 37444539, 2023).
melanoma (1 paper, 2026). A malignant, usually aggressive tumor composed of atypical, neoplastic melanocytes. "This dependency is not restricted to a specific melanoma differentiation state, but genetic depletion of CXXC1 (a complex-specific subunit) shows that CXXC1-dependent melanoma cells require Set1C/COMPASS activity to maintain global H3K4 trimethylation (H3K4me3) and proliferation." (PMID 41726895, 2026).
myeloma (1 paper, 2021). "In addition, myeloma cell dependency on CXXC1 was further validated by independent shRNA knockdown experiments." (PMID 34521827, 2021). "Six TFs (CXXC1, BPTF, MAZ, KLF13, CBFB and RFX5) were identified as showing higher connectivity in all myeloma subgroups compared to ND PC, thus exemplifying the process of existing TF ‘re-wiring’ in MM." (PMID 34521827, 2021).
tumor (5 papers, 2015 to 2023). "The CXXC1 locus encodes for a protein of the SETD1 complex, which acts as an epigenetic transcriptional activator; if deregulated, it can lead to tumor progression and poorer survival." (PMID 37175717, 2023). "Among highly perturbed gene pairs across multiple tumor types, we noted CXXC1, HSPA5, GSK3A, SERP1, PDIA6, FKBP14, and SCH1, which showed multiple co‐expression changes." (PMID 34698427, 2021). "Interestingly, there was no significant changes between tumor and normal tissue in enzymes writing or erasing H3K4 marks including Kmt2a, Ash1l, Cxxc1, Kdm1a and Ezh2." (PMID 25823816, 2015).
cancer (1 paper, 2021). A tumor composed of atypical neoplastic, often pleomorphic cells that invade other tissues. "Although little is known about the role of CXXC1 in cancer, it has been reported that its overexpression portends adverse prognosis in all stages of gastric cancer." (PMID 34521827, 2021).
CXXC1 also shares sentences with these, for which no sentence is quoted: lung adenocarcinoma (1 paper); osteoporosis (1); ovarian carcinoma (1); prostate carcinoma (1); synovial sarcoma (1); uterine corpus endometrial carcinoma (1).